CDC20 (cell division cycle 20)
Diseases named in the same sentence as CDC20 in open-access papers (continued):
Sharing a sentence is not in itself a finding about the gene and the disease.
cancer (continued). "At present, many studies have shown that the hub genes CDC20, CDK1, BUB1, CCNB1, and BUB1B identified in our PPI network are involved in cancer progression." (PMID 35664322, 2022). "CDC20, an APC activator and substrate, is often overexpressed in cancer cells, while impairment of CDH1 leads to genome instability and cancer development." (PMID 36077749, 2022). "Therefore, CDC20 may become a promising therapeutic target in the fight against human cancer." (PMID 35800227, 2022). "Based on The Cancer Genome Atlas (TCGA) and The Human Protein Atlas (THPA) databases, CDK1 and CDC20 were upregulated in LUSC at the mRNA and protein levels." (PMID 34307447, 2021). "Therefore, inhibition of CDC20 expression may be an effective cancer treatment." (PMID 34753395, 2021). "Therefore, our understanding of how Cdc20 functions in different cancer and its exact biological role in specific cancer types are limited and need to be clarified, which could further guide the molecular exploration and targeted therapy of Cdc20 in cancer research." (PMID 34527589, 2021). "Previous studies have shown that in actively dividing cancer cell lines, simultaneous depletion of CDH1 and CDC20 adaptor proteins, together with EMI1, i.e., three subunits of the APC/C, leads to a completely dysfunctional APC/C and a prolonged S-phase." (PMID 32295923, 2020). "The genes CDC20, CDCA8, and CEP55 were prognostic in more than three (multiple) cancer types while other genes were specific for particular cancer types, such as MYEOV for PAAD." (PMID 32489468, 2020). "For example, CDC20 is overexpressed in both CRC cell lines and primary cancer tissues compared to normal colorectal epithelial cells and paracancerous tissue samples." (PMID 32932732, 2020). "Chemicals that inhibit the SAC, such as TTKi’s and M2I-1, have been shown to block CDC20 sequestration by the MCC, leading to activation of the APC and effective cancer cell death." (PMID 32805721, 2020). "A recent study found that patients with overexpression of BUB1B, CDC20, CCNA2 and CDK1 were more likely to exhibit the worst cancers." (PMID 32805721, 2020). "Targeting APC activity has shown promise in an anti-tumor capacity, as the SAC inhibitors M2I-1 and TTKi, which both disrupt CDC20-SAC interactions, increase APCCDC20 activity and provide increased killing of cancer cells." (PMID 32805721, 2020). "While the consequences of Cdc20 depletion were mostly studied in MEF, we interrogated three different human cancer cell lines, showing similar effects." (PMID 32203171, 2020). "Several genes, including CCNB1, CDC20, CDC6, PLK1, and PTTG1, had multiple roles as core essential genes, oncogenes, and roles as hallmarks of cancer and in KEGG pathways." (PMID 32040444, 2020). "Increasingly studies have revealed that several genes related to cell cycle such as CDC20, TOP2A, BUBI, BUBIB, and UBE2C, are related to the occurrence and development of cancer, which were also identified in the present study." (PMID 33186389, 2020). "Several of these genes are involved in pathways that define the hallmarks of cancer, such as VEGFC (lymphangiogenesis), CASP2 (apoptosis and cell stress), and CDC20 (cellular proliferation)." (PMID 30866919, 2019). "Our evaluation revealed that CP5V (apcin-A-PEG5-VHL Ligand 1) was the most potent Cdc20 PROTAC in degrading Cdc20 and suppressing cancer cell growth." (PMID 31669221, 2019). "Thus, targeting CDC20 in cancer may be a potential treatment strategy." (PMID 31870357, 2019). "While apcin, TAME, proTAME and apcin-A have shown an inhibitory role in suppressing Cdc20-APC/C function, their limited efficacy in killing cancer cells remains a challenge for clinical translation." (PMID 31669221, 2019). "Pathway results showed that seed genes PTGS2, HDAC1, JUN, and SLC2A1 were enriched in pathway in cancer, seed genes HDAC1 and CDC20 were involved in cell cycle, and seed gene MTHFR participated in methane metabolism." (PMID 27034707, 2016).
cancer (continued). "From the cancer pathway-related genes analyzed, eight were down-regulated ~ 2- to 5- fold after CYP1B1 depletion and among them, CDC20 was the greatest." (PMID 26626260, 2015). "In this study, the expression levels of CDC20, BUB1, MCM2, and cyclin B1 were upregulated in the 3 and 10 μmol/l genistein groups, indicating the promoting effects of genistein on cancer cell proliferation." (PMID 25385471, 2015). "There are already a precedent for the roles of unregulated CDC20, RAD51, and CHEK1 in cancer development and progression." (PMID 25763370, 2015). "High expressions of cell division cycle 20 homolog (CDC20) and MAD2, key components of SAC, have been reported in various carcinomas." (PMID 25705694, 2015). "For instance, SMC1A, CDC20, SMAD3 and BUB1 are all example AbG-0.5 kb genes known to promote cell cycle progression and proliferation in various cancer cell types." (PMID 24086155, 2013). "The third group contains four mitotic proteins (ANAPC5, CDC16, CDC20, CDC27) and shRNAs targeting these mitotic genes are predicted to sensitize cancer cells to GSK461364A." (PMID 22248814, 2011). "Amongst these are regulators of mitosis e.g. BUB1, CDC20, and PBK, which are known to play important roles in the ontology of various types of cancers." (PMID 18847459, 2008). "CDC20, KIF20A and PTTG1 combined knockdown inhibited cell viability and DNA replication in both LGG (LN229/HS683) and GBM (U87MG/U343) cancer cell lines." (PMID 40047299, 2025). "Here we explore peptide inhibitors of Cdc20, a substrate-recognition subunit and activator of the E3 ubiquitin ligase the anaphase-promoting complex/cyclosome (APC/C) that is essential in mitosis and consequently of interest as an anti-cancer target." (PMID 40888475, 2025). "Pixuvri’s multitarget approach, which targets proteins like BubR1, Cdc20, MAD2, and TPX2, could circumvent these resistance mechanisms, offering a more effective strategy against drug-resistant cancers." (PMID 40519296, 2025). "CDC20 overexpression is known to be a negative prognostic marker in multiple cancer types, possibly due to its association with higher tumor cell division rate." (PMID 39838194, 2025). "Therefore, exploring the efficacy and safety of CDC20 inhibitors in the treatment of tumors, as well as the possibility of the combination of CDC20 inhibition with other therapeutic targets, may represent a promising avenue for future interventions in the treatment of malignant tumors." (PMID 39125953, 2024). "We found that treatment with Cdc20 inhibitors, such as apcin and Taxol, significantly reduced TPD52 polyubiquitination and degradation and proved to have an excellent synergistic effect with tunicamycin in cancer treatment." (PMID 39401430, 2024). "However, studies investigating the overexpression of CDC20 and CCNB1 have yielded varying results depending on cancer type." (PMID 39795587, 2024). "Cdc20 catalyzes the polyubiquitination of TPD52 to mark it for degradation, leading to the downregulation of ATF6 and ER stress as well as the progression of cancers." (PMID 39401430, 2024). "We observed that the protein levels of CDC20 and BUBR1 were decreased by ≈50% in CCDC68‐knockout HCT116 cells during late prometaphase, suggesting that CDC20 and BUBR1 protein levels were at least partly maintained by CCDC68 in cancer cells with low aneuploidy rates." (PMID 39018254, 2024). "Under these conditions, the top non-AR regulated gene was found to be CDC20, a key regulator of the spindle assembly checkpoint with an oncogenic role in several cancer types." (PMID 37509260, 2023). "CDC20 and PLK1 are both located at chromosomal region 9p, which is often amplified in cancer." (PMID 37509260, 2023). "As both CDC20 and KMT5A are up-regulated in cancer via a number of mechanisms, the relationship between the two proteins may be dysregulated, thereby promoting genomic instability." (PMID 37509260, 2023).
cancer (continued). "Among them, Apcin and pro-TAME have been identified as selective CDC20 and APC/CCDC20/APC/CCDH1 inhibitors, respectively, and are currently under preclinical investigation for their efficacy against different cancer subtypes, including hematological malignancies." (PMID 35490245, 2022). "The protein immunohistochemical staining indicated the levels of CDC20 and KIF2C were nearly the same in normal and cancer tissues, which was inconsistent with the result that the expression levels of CDC20 and KIF2C in tumor tissues were higher than normal tissues." (PMID 35456460, 2022). "There is evidence that CDC20, TTK, and CENPA were expressed and active in several types of cancer." (PMID 36213834, 2022). "Cluster 1 has the maximum score 27.676, with 38 nodes and 512 edges, including known cancer-related genes, such as BUB1 (mitotic checkpoint serine/threonine-protein kinase BUB1), CDC20 (cell division cycle protein 20 homolog), and PLK1 (serine/threonine-protein kinase PLK1)." (PMID 34512870, 2021). "We found that the deletion of CDC20, CDC25, or PLK1 genes is lethal for all cancer cell lines." (PMID 34887439, 2021). "The expression levels of UBE2S, PTTG1, and CDC20 were significantly higher in most cancer tissues than in normal tissues." (PMID 34726341, 2021). "Based on our findings, we have concluded that combinatorial treatment by CXCR4-ligand modified L1-polyplexes formed with AQP3, CDC20, and COL4A2 siRNAs effectively inhibits proliferation of TNBC cells and can be suggested as useful tool for RNAi-mediated cancer therapy." (PMID 34681181, 2021). "Interestingly, the genes CDC20, CDCA8, MYBL2, C1QTNF6, CEP55, CDK1 and KIF14 were found to be more universal/common, since they mark multiple types of cancers not only in prognosis but also in diagnosis." (PMID 32489468, 2020). "Owing to the pivotal role of Cdc20 in both mitotic exit and carcinogenesis, the development of small molecule inhibitors targeting Cdc20 to suppress Cdc20-APC/C activity has attracted substantial attention in the field of cancer therapy." (PMID 31669221, 2019). "While CP5V demonstrates a robust ability in degrading Cdc20, altering cyclin B levels, inducing mitotic arrest and promoting cancer cell death, the working concentration at 2 μM for CP5V still needs to be improved, and there are several strategies to improve the potency of anti-Cdc20 PROTAC." (PMID 31669221, 2019). "In addition to GTSE1, overexpression of CDC20, PCNA, and MCM has been detected in many types of human cancer." (PMID 32082966, 2019). "Given the importance of Cdc20-APC/C in carcinogenesis and the current challenges for developing potent inhibitors, we have utilized the PROTAC platform to design a new targeting approach by promoting the degradation of Cdc20 in cancer cells." (PMID 31669221, 2019). "CDC20 is an APC coactivator, and high APCCDC20 may be inappropriately driving cells through mitosis to promote genomic instability and cancer progression, inferring that APC inhibition will be beneficial." (PMID 29954095, 2018). "According to our analysis, these levels imply that free MCC2 is either not formed at all or highly unstable in these cancer cells in order to allow checkpoint proficiency at higher Cdc20 concentrations." (PMID 30199529, 2018). "Small molecules could be designed to disrupt the interactions between Cdc20 and SMAR1, to help restore the tumor suppressive function of SMAR1, leading to improved cancer therapy in the future." (PMID 28617439, 2017). "Interestingly, the partners of ANAPC2, CDC20 and CDH1, were also upregulated in this tumor, and APC/C has a recently-documented important role in cancer, and can be inhibited with a small molecule (Tosyl-L-Arginine Methyl Ester)." (PMID 25155515, 2014).
cancer (continued). "Previous research from our laboratory demonstrated that proTAME-containing therapies reduced CDC20 expression and increased the Bax/Bcl-2 ratio in RT4 cells, promoting apoptosis, while reducing this ratio in ARPE-19 cells, indicating a selective effect on cancer cells." (PMID 40136519, 2025). "While CDC20 may be pro-oncogenic, it is unlikely to act in isolation, as at least 60 of the known 69 human APC substrates are associated with multiple cancer types when they accumulate, and are now considered a cancer signature." (PMID 38730707, 2024). "Recently, suppression of Anaphase-Promoting Complex/Cyclosome-Cell Division Cycle 20 (APC/C-CDC20) activity using CRISPR/Cas9 mutagenesis has been reported to increase sensitivity to Kinesin Family 18a (KIF18a) inhibition, which functions to suppress multipolar mitotic spindles in cancer cells." (PMID 38928036, 2024). "Therefore, it is likely that that Frondoside A inhibits the proliferation and metastasis of cancer cells by down-regulating CDK1, CDC20, TOP2A and up-regulating CNN1.It should be noted that the free binding energy between Frondoside A and CDK1 was the lowest, measuring -10.7 kcal/mol." (PMID 38144520, 2023). "However, the correlation between CDC20 and cancer patients' prognosis has not yet been systematically evaluated." (PMID 36479068, 2022). "Hence, SKP2, instead of CDC20, positively correlates with YAP1 expression in pan-cancer." (PMID 35685435, 2022). "Cdc20 overexpression is accompanied by the overexpression of various other genes associated with APC/C impairment in diverse cancers, including overexpression of other APC/C substrates, indicating that impairment of the APC/C and not specifically Cdc20 overexpression is important for tumorigenesis." (PMID 35832196, 2022). "Moreover, the pan-cancer analysis of the molecular function of Cdc20 indicated that BUB1, CCNA2, CCNB1, CDK1, MAD2L1, and PLK1 might play a critical role in interaction with Cdc20." (PMID 34527589, 2021). "But the exact cancer types, in which Cdc20 could be potentially targeted, have not been clearly identified." (PMID 34527589, 2021). "In addition, CDC20, CDK4, MCM6, MAD2L1, MCM2 and MCM5 were leading genes intersecting in these four pathways, and a positive correlation between mRNA expression and LACTB was observed in most normal and cancer tissues." (PMID 33507917, 2021). "Although CP5V may be useful in targeting cancer cells that depend upon the over-expression of CDC20 protein, it remains unclear whether it can decrease CDC20 levels in cancers cells relative to healthy human cells without inducing general cytotoxicity that would be deleterious." (PMID 40650052, 2025). "Furthermore, we wondered whether the expression of CDC20 could be dramatically increased in the late stage of cancer, but not the early stage." (PMID 34527589, 2021). "Furthermore, use of the pharmacological agents APCIN or pro-TAME, which inhibit the binding of CDC20 to the APC (and thus APCCDC20 formation) resulted in increased apoptosis and death in multiple cancer cell lines, indicating that inhibition of the APC may be a useful anticancer approach." (PMID 32805721, 2020). "This knowledge has contributed to a hypothesis that inhibiting APC/CCdc20 might be an effective anti-cancer strategy in cells treated with microtubule poisons, which has led to studies targeting APC/CCdc20 using small molecule APC/C inhibitors and by targeting Cdc20 using RNAi." (PMID 29883473, 2018). "Moreover, cdc20 could also interact with USP24 when these residues were phosphorylated, implying that the decrease in USP24 during mitosis might be important for cell cycle progression and cancer cell proliferation." (PMID 27991932, 2017). "Thus, it is not surprising that several studies have shown that CDC20 may function as an oncoprotein to promote the development and progression of human cancers." (PMID 26561808, 2015).
cancer (continued). "Genetic mouse models lacking either CDC20 or CDH1 are lethal, highlighting the necessity of fine dose management should APC inhibitors, such as APCIN and/or TAME, be considered in the future for human cancer therapy." (PMID 38730707, 2024). "For CDC20, its negative correlations with the LN_IC50s of 18 anti-cancer drugs were shown, indicating its positive correlation with the sensitivities of HCC to the 18 anti-cancer drugs." (PMID 36494696, 2022).
tumor (222 papers, 2011 to 2026). "GSEA results showed that CDC20 highly expressed specimens were enriched in signaling pathways that are closely associated with tumor development, such as E2F, TARGETS, G2M checkpoint, and inflammatory response pathways." (PMID 41374402, 2025). "For instance, our study showed that the overexpression of NUAK1, LRRC17, FOXM1, and CDC20 as well as the downregulation of FLRT2 are associated with DNA repair pathway as well as tumor invasion pathways." (PMID 39149564, 2024). "CDC20 expression showed a significant positive correlation with tumor grade, indicating that higher CDC20 levels were associated with more aggressive tumor phenotypes." (PMID 39795587, 2024). "Our results, which demonstrate that CDC20 overexpression is linked to higher tumor grades in BC, support these findings." (PMID 39795587, 2024). "CDC20 knockdown by transduction with shCDC20 caused loss of tumor-initiating cells in the S, M, and G2 cell cycle phases and accumulation in the G1 phase." (PMID 36238156, 2022). "CDC20 participates in the pathogenesis of NSCLC, and elevated expression of CDC20 is associated with higher tumor grade and stage." (PMID 34307447, 2021). "Increased CDC20 expression has been associated with defective spindle formation and progression of multiple tumours, including HCC." (PMID 33541355, 2021). "A mistake during the segregation of sister chromatids prevents mitotic arrest due to abnormal levels of CDC20 thus contributing to premature anaphase and causing aneuploidy, which is associated with malignant transformation of the tumor cells." (PMID 34307447, 2021). "This suggests that the role of CDC20 in regulating the underlying mechanisms of tumorigenesis and progression is identical in different tumours." (PMID 32047816, 2020). "HSF1 is able to associate with cell cycle regulators cdc20 and polo-like protein kinase 1, participating in the regulation of tumor cell chromosomal stability." (PMID 25199534, 2014). "Quantitative CDC20 protein expression levels were significantly associated with PDAC tumor differentiation (P = 0.020)." (PMID 22475564, 2012). "Only tumor differentiation was significantly associated with CDC20 protein expression levels (P = 0.020)." (PMID 22475564, 2012). "Finally, we focused on the gene CDC20 to explore its impact on malignant phenotypes of tumor cells both in vitro and in vivo and elucidate its underlying mechanism." (PMID 39114311, 2024). "Similarly, in BC patients, CDC20 expression is positively associated with age, advanced tumor stage, HG tumor, distant metastasis, shorter recurrence-free survival, and worse overall survival." (PMID 39795587, 2024). "Dysregulation of the CDC20-hnRNPU axis is implicated in tumor growth and treatment resistance." (PMID 38577593, 2024). "Notably, the overexpression of CDC20 was significantly associated with sex, tumor differentiation, and TNM stage." (PMID 37383715, 2023). "In addition, CDC20 was linked to tumour mutation burden (TMB), immune checkpoint molecules, tumour microenvironment, and immunological infiltration." (PMID 35800227, 2022). "CDC20 was also reported as a hub protein among tumor-associated genes in DLBCL." (PMID 35490245, 2022). "In addition, the GInLncSig model is strongly associated with tumor mutant phenotype and CDC20 expression in LGGs, both of which are essential clues of genomic instability." (PMID 35069679, 2021). "Even more, high expression of CDC20 was associated with high tumor grade." (PMID 31991631, 2020). "Moreover, Cdc20 upregulation was associated with aggressive tumor progression and poor prognosis in gastric cancer and primary non-small cell lung cancer." (PMID 31669221, 2019). "However we detected individual somatic variants in known oncogenes (e.g. PIK3CA) and tumor suppressors (e.g. CDC20)." (PMID 30870501, 2019).